CXCL12 (C-X-C motif chemokine ligand 12)
Diseases named in the same sentence as CXCL12 in open-access papers (continued):
Sharing a sentence is not in itself a finding about the gene and the disease.
pulmonary fibrosis (continued). "Recently, less cytotoxic, more potent, and stable CXCR4 inhibitors such as BL8040 and LY2510924 have been developed, and thus the effects of targeting the CXCL12/CXCR4 axis by CXCR4 inhibitors for the treatment of lung fibrosis should desirably be re-examined." (PMID 32708315, 2020). "Inhibition of this axis with neutralizing antibodies against CXCL12 significantly reduces the development of lung fibrosis." (PMID 32708315, 2020). "Inhibition of the CXCL12/CXCR4 axis by neutralizing antibodies reduces the development of lung fibrosis through regulation of pro-fibrotic monocyte recruitment." (PMID 32708315, 2020). "To explore the mechanism responsible for the increased number of megakaryocytes in BLM-induced lung fibrosis, we measured CXCL12 expression in the lung tissue of mice after BLM challenge by quantitative real-time PCR (qPCR)." (PMID 31501415, 2019). "These cells have been shown to be recruited to mouse lungs in models of bleomycin-induced pulmonary fibrosis through CXCL12/SDF-1, which interacts with CXCR-4." (PMID 30764496, 2019). "In this study, we demonstrated that the number of CD41+ megakaryocytes increased in bleomycin (BLM)-induced lung fibrosis tissues through the Chemokine (CXCmotif) ligand 12/Chemokine receptor 4 (CXCL12/CXCR4) axis." (PMID 31501415, 2019). "Our data show that FBP-treatment 1) decreases bleomycin-induced pulmonary fibrosis in mice, 2) inhibits inflammatory cell migration to the lungs of mice, and 3) decreases CXCL12 expression levels in healthy and fibrotic mouse lung fibroblasts in vitro." (PMID 31509566, 2019). "CXCL12 promotes pulmonary fibrosis by recruiting “fibrocytes” and bone marrow-derived stem cells to injured lung." (PMID 29347981, 2018). "Several reports showed that treatment of mice with a CXCL12 antibody or CXCR4 antagonist (AMD3100) diminished bleomycin-stimulated lung fibrosis." (PMID 29499695, 2018). "In-vivo studies targeting CXCL12 in lung fibrosis models have overall been inconclusive, however they have demonstrated some success in the slowing of disease progression." (PMID 29507348, 2018). "In idiopathic pulmonary fibrosis, the interaction of CXCL12 and CXC receptor 4 (CXCR4) plays a critical role in lung fibrosis." (PMID 29499695, 2018). "Based on these and other observations, it has been proposed that CXCL12 chemoattracts BMDMSC and circulating fibrocytes to the lung via CXCR4/CXCL12 signaling during lung fibrosis." (PMID 26998906, 2016). "Modulation of chemokine CXCL12 and its receptor CXCR4 has been implicated in attenuation of bleomycin (BLM)-induced pulmonary fibrosis and carbon tetrachloride (CCl4)-induced hepatic injury." (PMID 26998906, 2016). "Fibrocytes also express several chemokine receptors, particularly CXCR4, which has been shown to mediate the effect of stromal derived factor-1 (SDF-1/CXCL12), a specific ligand for CXCR4, in causing migration of fibrocytes in pulmonary fibrosis." (PMID 27309347, 2016). "In a mouse model of bleomycin-induced lung injury, circulating CXCR4+ fibrocytes infiltrated and contributed to lung fibrosis after homing in response to the lung-plasma CXCL12 gradient, suggesting an active traffic through this pathway." (PMID 27309347, 2016). "The role of CXCL12 in the recruitment of circulating fibrocytes to sites of chronic injury and repair was initially demonstrated in the bleomycin model of pulmonary fibrosis." (PMID 25214520, 2014). "A previous study indicated that CXCL12 is a potent chemoattractant for fibrocytes that contributes to pulmonary fibrosis." (PMID 25121739, 2014). "CXCL12 was first described as a factor produced by bone marrow stromal cells and is a potent chemoattractant for fibrocytes that contributes to pulmonary fibrosis." (PMID 25121739, 2014).
pulmonary fibrosis (continued). "This study indicated that CXCR4+cells are the predominant population of fibrocytes recruited to fibrotic lungs of mice in a bleomycin model of lung fibrosis and that neutralizing CXCL12 significantly reduced lung fibrosis." (PMID 24478703, 2014). "Other investigators have similarly reported significantly higher levels of CXCL12 in the plasma and lungs of patients with idiopathic pulmonary fibrosis compared with healthy controls." (PMID 21219601, 2011). "Fibrocytes were found to express CXCR4 and to migrate in response to CXCL12 in vitro and in vivo in a model of bleomycin-induced pulmonary fibrosis." (PMID 21219601, 2011). "Using the Robust Cell Type Decomposition algorithm to deconvolve spatial transcriptomic data, we identified Cxcr4+ macrophages and Cxcl12+ fibroblasts as central drivers of pulmonary fibrosis progression, revealing a distinct spatial co-localisation pattern between these cell populations." (PMID 42204838, 2026). "CXCL12 is a mediator that stimulates fibroblast recruitment and contributes to pulmonary fibrosis." (PMID 39023414, 2024). "Additionally, recent studies also demonstrated that agonizing CXCR7 contributed to therapeutic benefits in pulmonary fibrosis and acute MI, arguing for the importance of CXCL12/CXCR7 signaling." (PMID 34072818, 2021). "In addition, pharmacological inhibition of the CXCL12/CXCR4 axis with WZ811 significantly attenuated lung fibrosis after BLM challenge reflected by morphological changes, ɑ-SMA, Col III, and TGF-β1 levels, and HYP content." (PMID 31501415, 2019). "The CXCR4/ CXCL12 axis contributes to pulmonary fibrosis development." (PMID 28968441, 2017). "Therefore, the methods for promoting CXCL12 degradation have therapeutic potential for pulmonary fibrosis alleviation." (PMID 28968441, 2017). "In pulmonary fibrosis, published reports suggest that collagen production in the injured lung is derived from fibrocytes recruited from the circulation in response to release of pulmonary CXCL12." (PMID 26998906, 2016). "In addition, inhibition of CXCR4/CXCL12 had been shown to reduce lung fibrosis in a BLM induced murine model of PF." (PMID 26998906, 2016). "Several reports indicated that induction of CXCL12 plays an important role in pulmonary fibrosis." (PMID 25121739, 2014). "Circulating fibrocytes could directly be attracted to the alveolar space because of the local expression of chemokines for fibrocytes (such as CCL2 or CXCL12) already demonstrated in lung fibrosis." (PMID 23341987, 2013). "Since fibroblasts were known to be attracted by chemokine CXCL12 and may contribute to the development of lung fibrosis, we performed the chemotaxis assay and found consistent results that HL217 dose-dependently reduced TGF-β-stimulated migration responding to CXCL12 in both NHLF and DHLF-IPF." (PMID 37964270, 2023). "Moreover, the concentration of CXCL12 in the plasma of patients with idiopathic pulmonary fibrosis was significantly higher than in healthy controls, suggesting that circulating fibrocytes are recruited through the CXCR4 - CXCL12 axis and contribute to lung fibrosis in this patient population." (PMID 21219601, 2011). "Treatment of bleomycin-induced fibrotic rats with the CXCR4 antagonist, AMD3100, reduced CXCL12 levels in bronchoalveolar lavage (BAL) fluids, resulting in a reduction in pulmonary fibrocytes and an overall improvement in pulmonary fibrosis phenotypes." (PMID 36164329, 2022). "In a mouse model of lung fibrosis, it has been shown that human fibrocytes migrate in response to SDF-1/CXCL12 and localize to lungs if injected in bleomycin-treated animals." (PMID 34764871, 2021). "Recent studies established that CXCL12/CXCR4 axis characterizes the key pathway in regulation of fibrocyte migration and participates in pulmonary fibrosis." (PMID 29499695, 2018). "CXCL12 acts on CXC receptor 4 (CXCR4) receptors to promote fibrocyte homing to the lungs and further lead to pulmonary fibrosis." (PMID 29499695, 2018).
pulmonary fibrosis (continued). "Our findings display two pathways related with CXCL12 and CTGF, and offer the development of therapeutic approaches to diminish pulmonary fibrosis of IPF triggered by CXCL12." (PMID 29499695, 2018). "Specifically, inhibition of CXCR4/CXCL12 signaling with anti-CXCL12 antibody reduced recruitment of CD45+ ColI+ CXCR4+ fibrocytes in BLM exposed mice and reduced lung fibrosis." (PMID 26998906, 2016). "Previous reports indicated a critical role of the CXCL12/CXCR4 axis in fibrocyte migration in the lungs and its contribution to pulmonary fibrosis." (PMID 25121739, 2014). "CXCL12 is a ligand of the chemokine receptor, CXCR4, and plays an important role in pulmonary fibrosis." (PMID 25121739, 2014). "A large body of evidence has accumulated which suggests that CXCL12 and its receptor, CXCR4, participate in pulmonary fibrosis." (PMID 25121739, 2014). "CXCL12 (stromal cell-derived factor-1, SDF-1) is a potent chemokine for homing of CXCR4+ fibrocytes to injury sites of lung tissue, which contributes to pulmonary fibrosis." (PMID 25121739, 2014). "Previously, we had studied the role of the CXCL12/CXCR4-axis in a rodent model of bleomycin-induced lung injury and reported that TN14003 blocked bleomycin-induced lung fibrosis." (PMID 22485156, 2012). "Previous studies have demonstrated that the activation of CXCL12/CXCR4 signaling pathway could contribute the neutrophil accumulation and retention in the lungs during ALI and accelerate lung fibrosis." (PMID 38352962, 2024). "We hypothesized that proteins previously shown to be elevated in patients with pulmonary fibrosis (Amphiregulin, MMP-9, MMP-7, P-selectin, S100A12, and CXCL12) would be elevated in patients who develop fibroproliferative ARDS." (PMID 39106254, 2024). "In the lung fibrosis model, a single administration of bleomycin did not induce elevated CXCL12-levels by itself at day 21, however, compound 18a treatment did." (PMID 35562519, 2022). "However, UPR can also participate in pulmonary fibrosis by increasing the expression of profibrotic mediators, such as TGF-β1, platelet-derived growth factor (PDGF), CXCL12, and CCL2." (PMID 35935869, 2022). "Thus, our research suggests that pharmacological blocking of the CXCL12/CXCR4 axis can reduce megakaryocyte chemotaxis to damaged lung tissues, ultimately partially mitigating lung fibrosis." (PMID 31501415, 2019). "In general, CXCL12 triggers CXCR4 to activate G protein-coupled signaling pathways including mitogen-activated protein kinase (MAPK), which subsequently induce several cellular responses including gene expression and pulmonary fibrosis." (PMID 29499695, 2018). "CXCL12 recruits fibrocytes in a murine model of pulmonary fibrosis, but not in a model of wound repair." (PMID 18298660, 2008). "Notably, the pleiotropic activities of homeostatic CXCL12 and CCR7 in IPF encompass chronic lung inflammation, angiogenesis, and fibrosis, indicating diverse chemokine production triggering critical pathways in pulmonary fibrosis." (PMID 39768150, 2024). "Therefore, the CXCL12/CXCR4 axis and CTGF play important roles in pulmonary fibrosis." (PMID 25121739, 2014).
ischemia (63 papers, 2005 to 2025). A hypoperfusion of the BLOOD through an organ or tissue caused by a PATHOLOGIC CONSTRICTION or obstruction of its BLOOD VESSELS, or an absence of BLOOD CIRCULATION. "Locally administered CXCL-12 also promoted EPCs accumulation at the site of ischemia, associated with ischemic neovascularization." (PMID 33946931, 2021). "Activation of the CXCL12/CXCR4/ACKR3 axis is known to aid myocardial repair through ischemia-triggered hypoxia-inducible factor-1α (HIF-1α)." (PMID 38994928, 2024). "HIF-1α is a crucial transcription factor in the cardiovascular system, as it regulates gene expression of the CXCL12/CXCR4/ACKR3 axis during ischemia." (PMID 38994928, 2024). "Another protein upregulated by HIF-1α is CXCR4, a chemokine receptor for SDF-1α also known as CXCL12, whose expression occurs in hypoxic tumoral microenvironment conditions and vascular ischemia." (PMID 32599834, 2020). "As the wound is virtually ischemia from the disruption of its vascular supply, CXCL12 aids in the response to ischemia by enhancing angiogenesis and vasculogenesis." (PMID 28117733, 2017). "Via the sympathetic nerve system and the adrenoreceptor β3 the systemic effects of ischemia result in a decrease of bone marrow derived CXCL12 and other retention factors." (PMID 25152735, 2014). "Animal studies indicate a beneficial role for CXCL12 in post-ischemia white matter injury, whereas antagonist studies provide evidence that an internalization of CXCL12 by ACKR3 and the resulting decline of CXCL12 allow consecutive inflammatory parenchymal infiltration." (PMID 29792190, 2018). "It has been proposed that CXCL12 via its CXCR4 receptor plays a role also in regulating the survival and migration of NSCs in response to CNS trauma, such as brain tumors, ischemia, and neuroinflammation-associated disorders, and in regulating the migration and survival of OPCs in vitro." (PMID 26747276, 2016). "In addition to its role in vascularization during development, the CXCL12/CXCR4 also plays an important role in angiogenesis in the context of ischemia, as discussed in more detail recently." (PMID 26347749, 2015). "CXCL12 is considered to be the main chemokine involved in ischemia-directed CAC mobilization and homing, occurring along a (reversed) BM-to-PB CXCL12 gradient." (PMID 24288546, 2013). "The degree to which chemotactic factor CXCL12 is expressed at the BCI reasonably relates to the degree of cell injury and ischemia resulting from the effects of electrode implantation, and the activity of the signaling, both in the acute and the chronic circumstances." (PMID 40801596, 2025). "Moreover, downregulation of CXCL12/CXCR4 inhibits glial TLR4 activation in the spinal cord and alleviates pain in the ischemia-reperfusion-induced inflammatory pain model." (PMID 30647535, 2018). "CXCL12 is the single natural ligand for the chemokine receptor CXCR4 and the CXCL12/CXCR4 axis is important in the mobilization, migration and recruitment of EPCs to sites of ischemia." (PMID 27834814, 2016). "In vivo, the role of CXCL12 and its CXCR4 receptor in promoting the differentiation of OPCs and their remyelination has been demonstrated in mice following cuprizone-induced demyelination and ischemia-induced demyelination." (PMID 26747276, 2016). "Recently, it has been found that both chemokine C-X-C motif ligand 12 (CXCL12) and its receptor CXCR4 were upregulated in spinal glial cells of mice with partial sciatic nerve ligation (pSNL)-induced neuropathic pain or chronic post-ischemia-induced inflammatory pain." (PMID 29386025, 2018). "Furthermore, both CXCL12 and MIF play a protective role in MI-ischemia-reperfusion injury." (PMID 26257740, 2015).
rheumatoid arthritis (61 papers, 2005 to 2026). A chronic, systemic autoimmune disorder characterized by inflammation in the synovial membranes and articular surfaces. "The CXCL12-CXCR4 axis is known to be of great importance in rheumatoid arthritis where abnormally high concentrations of CXCL12 in synovial fluid and overexpression of CXCL12 in synovial cells have been found." (PMID 40453083, 2025). "As CXCR4 is up-regulated in Classical Monocytes from rheumatoid arthritis patients, they can be expected to migrate towards CXCL12." (PMID 40453083, 2025). "The clinical relevance of the CXCR4/CXCL12 axis has been demonstrated in rheumatoid arthritis and multiple sclerosis." (PMID 37736772, 2023). "The CXCL12/CXCR4 axis has been implicated in the pathogenesis of several types of inflammatory arthritis and autoimmune diseases, including rheumatoid arthritis (RA), osteoarthritis (OA), systemic lupus erythematosus (SLE), and ankylosing spondylitis (AS)." (PMID 36979628, 2023). "In this model of rheumatoid arthritis, the fibroblast secretion of IL-6, CXCL12, and CCL2 in the synovial microenvironment, as well as the expression of an IFN-γ gene signature, stimulates the macrophage-mediated inflammatory response." (PMID 36559029, 2022). "Accumulating evidence demonstrates that CXCL12 upregulation was implicated in AADs including IPF, rheumatoid arthritis (RA), and amyotrophic lateral sclerosis (ALS)." (PMID 35347083, 2022). "In this study, we found that the hub gene C3 was enriched in SLE, and CXCL12 was enriched in rheumatoid arthritis." (PMID 36398072, 2022). "CXCL12 has been shown to be upregulated in rheumatoid arthritis synoviocytes and influences T-cell accumulation in the disease." (PMID 26198319, 2015). "In pathologies such as rheumatoid arthritis, IL-18 has been shown to promote migration, adhesion and activation of leucocytes through the release of different factors such as SDF1/CXCL12 and VCAM1/ICAM1." (PMID 24778454, 2014). "Early studies showed that the CXCL12/CXCR4 chemokine axis is involved in several inflammatory diseases such as rheumatoid arthritis, acute lung injury, and sepsis." (PMID 22073304, 2011). "The CXCL12/CXCR4 chemokine axis is involved in several inflammatory diseases such as rheumatoid arthritis, acute lung injury, and sepsis." (PMID 22073304, 2011). "Specifically, there is increasing evidence that CXCL12 plays a crucial role in patients with rheumatoid arthritis (RA)." (PMID 16277673, 2005). "Thus, the CXCL12/CXCR4 axis is associated with various infectious and inflammatory diseases, including osteoarthritis (OA) and rheumatoid arthritis (RA)." (PMID 41331944, 2025). "CXCL12+ fibroblasts included an inflammatory CD74hiHLAhi cluster (F-5) and a CXCL12+SFRP1+ cluster (F-6) with the highest levels of IL6, which encodes a proven drug target in rheumatoid arthritis." (PMID 37938773, 2023). "CXCL12 sustains and promotes the progression of rheumatoid arthritis." (PMID 36725964, 2023). "In addition, CXCL12 was enriched in rheumatoid arthritis (hsa05323), and C3 was enriched in leishmaniasis (hsa05140)." (PMID 36398072, 2022). "In addition, CXCL12 and CXCL12γ were displayed on HSPGs by endothelial cells in rheumatoid arthritis (RA) synovium." (PMID 32296423, 2020). "Furthermore, CXCL12 plays a role in several autoimmune diseases like rheumatoid arthritis (RA) and multiple sclerosis (MS)." (PMID 27566567, 2016). "Beyond the tumour microenvironment, CXCL12 may play an important role in the pathogenesis of rheumatoid arthritis." (PMID 24961933, 2014). "We previously demonstrated that TMEM230 and RNASET2 were downregulated in CXCL12 expressing synovial fibroblast cells of rheumatoid arthritis (RA) compared to osteoarthritis (OA) patients." (PMID 40862725, 2025). "In rheumatoid arthritis (RA), the expression of CXCL12 in synovial tissues is increased, and CXCL12 seems to be predominantly expressed by endothelial venules and synoviocytes in the synovial tissues." (PMID 31024553, 2019).